CD44 (CD44 molecule (IN blood group))
Diseases named in the same sentence as CD44 in open-access papers (continued):
Sharing a sentence is not in itself a finding about the gene and the disease.
tumor (continued). "Here, we observed high contribution of the CD44+/CD24− population in the BrCCh1 ER-poor/PGR-poor/Her2low tumour cell line, in which the phenotype is relatively close to TNBC." (PMID 29986702, 2018). "CD44 has a pivotal role in regulating the properties of CSCs, including their self-renewal, tumor initiation, metastasis, and chemoradioresistance." (PMID 30177680, 2018). "HA tetrasaccharide glycoclusters were constructed on the dendrimers as targeting for tumor cells highly expressing CD44." (PMID 29899207, 2018). "Once CD44−CD24+ cells collected by bone lesions were re-injected in mice, they formed new tumor masses, with a heterogeneous population, constituted mainly by CD44+CD24− cells." (PMID 29461491, 2018). "We further evaluated the correlation between the expression of SALL4 and CD44 using the marker-selected NSCLC cells to initiate in vivo tumor by subcutaneous injection into nude mice." (PMID 29691367, 2018). "Various CD44 isoforms are expressed in several cancer stem cells during tumor progression and metastasis." (PMID 30402042, 2018). "A preclinical dose escalation study with 89Zr-labelled RG7356 confirmed tumour targeting of CD44+ tumours in xenograft-bearing mice." (PMID 29356983, 2018). "On the contrary, Horimoto and co-authors demonstrated that ER-positive patients with CD44+/CD24− tumours had significantly longer disease-free survival than all other ER-positive patients." (PMID 29986702, 2018). "This is consistent with the reduction of OCT4, NANOG and SOX2 expression, reduction in the BCSC population by loss of the ALDH1 and CD44+/CD24– population, the deformation of mammospheres, and the strong reduction in animal tumor volume and tumor weight." (PMID 30542507, 2018). "HA, as a targeting molecule for a CD44-contained delivery system, increases intracellular drug concentration in tumor tissue." (PMID 29899207, 2018). "Immunofluorescence assay showed that ALDH1+ BCSCs and CD44+CD24− BCSCs are localized in different regions within the tumour tissue." (PMID 29780673, 2018). "Increased CD44 expression has been associated with ERK1/2 phosphorylation, and increased tumor aggressiveness." (PMID 29669525, 2018). "The MAPK pathway, which is frequently hyperactivated in tumors, can enhance the invasiveness of tumor cells by modulating the alternative splicing of CD44." (PMID 30241319, 2018). "Targeted deletion of CD44 in murine leukemogenesis model decreased the tumor burden in peripheral blood and spleen, resulting in a prolonged overall survival." (PMID 29747682, 2018). "CD44 is a cancer stem cell marker that plays a role in tumor metastasis and progression while regulating multiple signaling networks depending upon the isoforms expressed." (PMID 29880060, 2018). "CD44 showed positive immunostaining that was much stronger in the tumor cells in the periphery than in the core in patients with much higher CD44 mRNA expression in the periphery than in the core (patients with a high P/C ratio)." (PMID 30210550, 2018). "Maintaining the initial structure of HA without any chemical modification, HA-LPs showed a high accumulation ability in tumor site and a strong anti-tumor efficacy against H22 (murine hepatoma cells, which expressed CD44 highly)." (PMID 29378465, 2018). "CD44 antibodies conjugated to anti-tumor agents can be used to target CD44-expressing cancer cells or netballing antibodies that block CD44-mediated signaling were being developed for cancer therapy." (PMID 29747682, 2018). "The A2780 cells did not express PLXDC1 or CD44, whereas the tumor endothelial cells showed high expression of CD44." (PMID 29890852, 2018). "Meanwhile, studies have shown the surfaces of some tumor cells are rich in hyaluronic acid receptor protein CD44." (PMID 30567299, 2018). "We first analyzed CD44 expression and its ability to bind HA in all tumor cell lines to discard a different behavior as a consequence of the loss of CD44 expression." (PMID 30564299, 2018).
tumor (continued). "IL-12-LNP elicited marked infiltration of activated CD44+ CD3+ CD4+ T helper cells into the tumor, and increased the production of Interferon γ (IFNγ)." (PMID 30458889, 2018). "Although there are other HA receptors, we focused only on the interaction with CD44 because it is the main receptor involved in tumor processes." (PMID 30564299, 2018). "Mechanisms whereby tumours sustained HT under CD44-knockdown conditions include upregulation of PHGDH, PSAT1 and PSPH that drove glycolysis-dependent activation of serine/glycine-cleavage systems to provide one-methyl group for HT synthesis." (PMID 29674746, 2018). "Since it has been shown that a specific subpopulation of aggressive tumor cells is associated with stem cell-like properties, we assessed CD24, CD29, and CD44 expression in HSC-3 cells by flow cytometry." (PMID 30029671, 2018). "Due to ITGA2 upregulation and CD44 downmodulation after Maitake treatment, thus blocking tumor cell survival, metastasis, and arteriogenesis in tumoral MCF-7 cells." (PMID 29872510, 2018). "CD44 expression was statistically similar in inflammatory cells and benign epithelium (p = 0.862), but significantly weaker in neoplasia (p ≤ 0.001)." (PMID 29682524, 2018). "Previously, CD44 phenotype in 30 T-ALL cases was positively associated with increased CNS and tumor infiltrations." (PMID 30430079, 2018). "The tumor-initiating markers CD44, CD133 and LGR5 were markedly down-regulated after culture of IHCC organoids in DM in comparison to culture in EM." (PMID 29434290, 2018). "Quantification of representative tumor images confirmed that there was a significant increase of CD44+ immune cells in IL-12-LNP-treated mice." (PMID 30458889, 2018). "CD44 is a cell-surface glycoprotein overexpressed in most human tumors and plays a key role in tumor cell adhesion and migration." (PMID 30177521, 2018). "The binding of ERMs and adaptor proteins to the cytoplasmic portion of CD44 initiates changes in tumor cell cytoskeletal architecture and in cell signaling." (PMID 29747682, 2018). "Most stem cell markers were expressed at only a low level in the both core and periphery of the tumor, except for Sox2 and CD44, which showed high expression in both sites, and CXCR4, which showed slightly higher expression in the periphery." (PMID 30210550, 2018). "HA is a major ligand of CD44 and these receptors are over expressed in tumor cells, thus HA can be used for better targeting to cancer cells." (PMID 29534519, 2018). "A total of 113 patients with suspected EC had tumor samples analyzed for the prevalence of ALDH1 and CD44 expression, as well as the associations of both markers with patient clinicopathological parameters and OS." (PMID 30372483, 2018). "Conversely, FGFR2 overexpression increased CD44 expression and accelerated tumor growth in mice indicating the positive feedback mechanism in the regulation of CD44 and FGFR2 expression." (PMID 29747682, 2018). "Previous studies found that OPN modulates cell migration, EMT, ECM-invasion and stemness maintaining of tumor cell via binding integrins and CD44 or activating NF-Kb, MEK/MAPK, PI3K/Akt, and FAK pathways." (PMID 29415992, 2018). "Studying the expression of CD44 on tumour infiltrating ILC and peripheral blood confirmed high expression of CD44 on all ILC populations in patients with breast or malignant GI tumours." (PMID 29587679, 2018). "The present studies have focused on CD44, a transmembrane glycoprotein that is important for cell signaling and tumor stemness and metastasis." (PMID 29423071, 2018). "OPN promotes stem cell-like properties and radiation resistance in adjacent tumor cells via activation of CD44 signaling." (PMID 29747682, 2018). "Accordingly, staining intensities for Ki67 were greatly decreased in tumor tissues from mice with subcutaneous HCC implantation of CD133+/CD44+ shOPN cells." (PMID 30064482, 2018).
tumor (continued). "CD44/CD44v6 contribute to tumor cells leaving the mass of the primary tumor to circulate in blood and lymph and to settle in lymph nodes and distant organs, which is supposed to be linked to a subpopulation of CIC." (PMID 30211160, 2018). "CD44+/24-/low tumor cells was determined as the cells positive for black color but negative for red staining." (PMID 29423076, 2018). "The knockdown of CD44 or ALK4 with specific shRNAs largely eliminated the tumor growth in immunodeficient xenogenic hosts, indicated that signals through CD44 and ALK4 are interrelated and critical for tumor growth in vivo." (PMID 30061637, 2018). "The results recorded in this study also demonstrated that positive expression of CD44 in CAC was positively correlated with tumor differentiation, invasion, LNM stages, and TNM stages." (PMID 30021598, 2018). "It has also been demonstrated that CD44-targeting in xenografts results in tumor cell phagocytosis mediated by macrophages." (PMID 30200242, 2018). "The anti-CD44 antibody RG7356 prevented tumor cell adhesion to hyaluronic acid in vitro and caused tumor growth inhibition in vivo in xenograft models using cell lines expressing the CD44s isoform." (PMID 30200242, 2018). "Using FACS-based single-cell analysis, we examined the stem cell fate of freshly isolated tumor cells using common cancer stem cell markers, including CD44, CD24, and CD49f for breast CSCs." (PMID 29510720, 2018). "In highly invasive GBM, GSCs located in such an invasion niche are thought to promote tumor invasion by increasing the expression of CD44, resulting in early tumor progression or dissemination." (PMID 30210550, 2018). "The soluble CD44 ectodomain was used as a competitor of CD44 on tumor cells to compete out HA ligand as a potential therapeutic approach to inhibit tumor growth and metastasis." (PMID 29747682, 2018). "The flow cytometry analysis indicated that the percentage of CD133+/CD44+ cells in U87 tumor spheres was higher than U87 cells." (PMID 29416017, 2018). "And the expression of stemness markers, OCT4 and Nanog, which were down-regulated in tumor tissues from the subcutaneous implantation models of CD133+/CD44+ cells with shOPN/EV, were partly rescued by introduction of DNMT1." (PMID 30064482, 2018). "Bispecific CD44-EpCAM aptamer suppressed intraperitoneal tumor outgrowth more significantly than individual CD44 and EpCAM aptamers did alone or in combination through enhanced targeting of cancer cells." (PMID 29562664, 2018). "The CD44 protein, as a predominant receptor for hyaluronan (HA), is highly expressed on the surface of multiple tumor cells." (PMID 29899207, 2018). "The multifaceted interplay between CD44/CD44v6, signal transducing molecules and proteases facilitates the metastasizing tumor cell journey through the body." (PMID 30211160, 2018). "The CD44 protein is relatively static on the surface of many normal cells, whereas it is over-expressed and highly activated on the surface of tumor cells." (PMID 29899207, 2018). "Of note, we observed an increase in the number of CD44+ immune cells recruited to tumor and surrounding normal liver tissue in IL-12-LNP treated mice in comparison to control mice." (PMID 30458889, 2018). "In summary, hyaluronic glycocluster modified PAMAM dendrimer macromolecule was successfully constructed as a targeted delivery vector for gene drug siRNA delivery to CD44 over-expressed tumor cells." (PMID 29899207, 2018). "Cultured GSCs obtained from the tumor periphery were highly invasive and have enhanced migration phenotype, both of which were markedly inhibited by CD44 knockdown." (PMID 30210550, 2018). "Altogether, we conclude that IL‐4 is a regulator of basal‐like cells showing characteristics of tumor‐initiating cells by inducing expression of CD44." (PMID 29236307, 2018). "High molecular weight HA combined with the CD44 receptor can induce CD44 aggregation on the surface of the tumor, thereby preventing the cellular uptake of the drug." (PMID 29899207, 2018).
tumor (continued). "And both the in vivo tumor formation latency and tumor size were closely correlated with OPN level of CD133+/CD44+ cells." (PMID 30064482, 2018). "It is well documented that cancer cells positive for the cell surface antigens CD24, and CD44 exhibit increased self‐renewal and tumor‐initiating potential." (PMID 30318866, 2018). "In 2003, a CD44+/CD24− phenotype was first identified as a highly tumorigenic subpopulation of tumor cells with stem-cell-like characteristics." (PMID 29739401, 2018). "Osteopontin (OPN) also binds to CD44 inducing cell signaling that mediates tumor progression and metastasis." (PMID 29747682, 2018). "Immunohistochemical (IHC) staining demonstrated that 5-methylcytosine (5mC) was down-regulated in subcutaneous tumor tissues from implantation models of CD133+/CD44+ shOPN compared with CD133+/CD44+ SCR." (PMID 30064482, 2018). "Patients with CTCs expressing a cytokeratin epithelial marker and the CSC markers CD133 and/or CD44 had a higher risk of tumor recurrence and lower overall survival, compared to those with cytokeratin+/CD133−/CD44− CTCs." (PMID 29373514, 2018). "CD44 is a cell-surface glycoprotein that is overexpressed in most human tumors and modulates tumor cell metastasis via recruitment of CD44 to the cell surface." (PMID 30177521, 2018). "Comparable to a strong signal in tissue staining of the primary tumor, almost all cells from the primary cell culture (99.7%) were positive for CD44 in flow cytometry." (PMID 29693014, 2018). "Cerebral brain tissue samples adjacent to tumor areas with some visible gliosis showed abundant staining for hyaluronan and CD44." (PMID 29914429, 2018). "Little is known about the clinical significance of the GSCs highly expressing CD44 with such multifunctional activities, particularly, in the tumor progression of GBM." (PMID 30210550, 2018). "IBC down‐regulated ERα and CD44 expression and thus inhibited tumour growth in paclitaxel‐resistant xenograft models." (PMID 30179299, 2018). "The switch of CD44 isoforms as how this relates to their functional roles in adaptive plasticity of tumor cells is becoming more clearly delineated." (PMID 29747682, 2018). "CD44+ membrane staining and Ki67+ nuclear staining indicate highly proliferative, fast-growing human tumor cells." (PMID 30220977, 2018). "HA has been reviewed in the previous section; HA and its receptors (i.e., CD44), HA synthases (i.e., HAS1 and HAS2), and hyaluronidase (HYAL1, 2, 3) are all associated with tumor growth and progression." (PMID 30135409, 2018). "Further studies are necessary to elucidate the resistance phenotype by which CD44 expression is regulated by ERα in other hormone‐dependent tumours." (PMID 30179299, 2018). "Original tumor, R2J, cultured in monolayer (2D) and in spheres showed a persistence expression of CD44, CD56 (except in monolayer), EGFR, Ki67, Nestin, and vimentin." (PMID 30583471, 2018). "Recent evidence has reported that CD44 promotes tumor invasion andmetastasis in multiple cancer types including colon, prostate, bladder, breast, andliver cancers." (PMID 29515105, 2018). "In this paper, a special role of CD44+ -cells of the EC in initiation and maintenance of the tumor process in the EC under administration even in minimal doses has been shown." (PMID 28622715, 2017). "Biocompatible and biodegradable HA-coated CS NPs were developed to encapsulate a chemotherapeutic drug (5-Fu) to enhance drug accumulation in tumor cells and to improve the drug’s antitumor efficiency by achieving targeted drug delivery via CD44." (PMID 28068992, 2017). "It is of note that the CD44+ cell fraction resembled the primary tumor to a higher degree, since both samples lack the focal amplifications seen in the unsorted of pleura sample." (PMID 28423035, 2017).
tumor (continued). "Nevertheless, CD44+ cancer cell population in primary HNSCC is comprised of less than 10% of bulk tumor and HNSCC-driven squamospheres possessed enriched CD44+ cell population (53%)." (PMID 29029509, 2017). "In concordance with these findings, in gastric cancer, CD44 is also a marker of a phenotypic subgroup of CTCs known as tumor‐initiating cells (TICs), conferring a strong ability in these cells to induce disease recurrence and metastasis." (PMID 28700115, 2017). "We found a significant correlation (p < 0.0001, Fisher's exact test) between the Myc and CD44 co-localization within the primary TNBC tumor samples." (PMID 28427212, 2017). "Concurrently, TGFβ drives Notch1-mediated EMT to generate tumor initiating cells characterized by high CD44 expression." (PMID 29170450, 2017). "Using a chemoattractant (1% FBS), we observed that inhibition of CD44 expression abrogated the tumor cell ability to invade through a matrigel coated membrane." (PMID 28279210, 2017). "CD44 is a cell surface glycoprotein mediating cell adhesion and migration in a variety of pathophysiological processes, including tumor metastasis, wound healing, and inflammation." (PMID 28098144, 2017). "Further, we provide evidence that MCs can have a potential role in serglycin induced tumor progression by activating a CD44-related signaling pathway." (PMID 28445977, 2017). "The CD44 cell surface marker plays an important role in tumor cell proliferation and takes a key part in metastatic processes such as motility, migration and invasion." (PMID 28423035, 2017). "DN tumor cells display an intermediate immunophenotype between the DN1 (CD44+CD25–) and the DN2 (CD44+CD25+) differentiation stage." (PMID 29136506, 2017). "Patients with tumor CD44 expression have more aggressive, angiogenic, and radiation-resistant phenotypes but respond better to Temozolomide." (PMID 29259986, 2017). "Nanoparticles based on hyaluronic acid (HA) have received a wide attention for targeted cancer therapy as HA, a biocompatible and biodegradable natural polysaccharide, has an intrinsic binding affinity to CD44 that is overexpressed in many tumor cells." (PMID 28958164, 2017). "Herein, we report that miR-141 is under-expressed in CD44+ PCSCs from both xenograft and patient tumours, and miR-141 exhibits tumour and metastasis-suppressing effects in PCa." (PMID 28112170, 2017). "Histogram depiction of allele frequencies for bulk tumor, tumor EPCAM+CD44+CD49f+ cells, and lymph node EPCAM+CD44+CD49f+ cells illustrates the similarity among these fractions." (PMID 28487492, 2017). "Studies with tumor tissues from the BC patients who had already received chemotherapy revealed an increased percentage of mammosphere-forming cells with CD44+/CD24− phenotype subpopulation." (PMID 28445439, 2017). "Owing to its ability to specifically target CD44 receptors, HA has been frequently modified with a drug carrier to enhance drug delivery in CD44-overexpressed tumor cells to effectively inhibit tumor growth." (PMID 28068992, 2017). "The established fact of heterogeneity of the EC subpopulation composition is important and there has been emphasized the value of CD44+ subpopulation in maintaining the growth of this type of tumor." (PMID 28622715, 2017). "Compared to hATN, we found increased expression of versican, Adipo R1 and CD44 both in hATT attached to the tumor as well as in hATT 2 cm from the tumor." (PMID 28173833, 2017). "Owing to an extremely low level of CD24 positive cells in C666-1, only CD44, EpCAM and EpCAM/CD44-selected cells from C666-1 were evaluated for their tumour-initiating ability in NSG mice." (PMID 28959019, 2017). "None of the variants present in the lymph node EPCAM+CD44+CD49f+ cells were exclusive as they were present in at least two other tumor or primary tumor EPCAM+CD44+CD49f+ samples." (PMID 28487492, 2017).